GPRIN3 (GPRIN family member 3)
Description:
May be involved in neurite outgrowth.
Synonyms: GRIN3; FLJ42625
Tractability: Antibody: its Gene Ontology location is reachable by antibodies, with medium confidence. PROTAC: ubiquitination databases record sites on it; its protein half-life has been measured.
Gene: Protein-coding gene on chromosome 4 (89,236,383 to 89,307,937, reverse strand). Ensembl gene ENSG00000185477.
Subcellular location (Human Protein Atlas): Nucleoli; Nucleoplasm
Gene Ontology:
Biological process: neuron projection development
Cellular component: plasma membrane
Genetic constraint (gnomAD): Loss-of-function variants: 12 observed, 15.24 expected, observed/expected ratio (o/e) 0.79, 90% interval 0.5 to 1.27. The upper end of that interval is the gene's LOEUF score, 1.27, which puts it in group 5 of 6, group 1 being the genes least tolerant of losing a copy. Missense variants: 1,009 observed, 1,012.2 expected, observed/expected ratio (o/e) 1, 90% interval 0.95 to 1.05. Synonymous variants: 377 observed, 394.27 expected, observed/expected ratio (o/e) 0.96, 90% interval 0.88 to 1.04.
Homologues: Orthologues: chimpanzee GPRIN3 (99% identical), macaque GPRIN3 (94% identical), pig GPRIN3 (70% identical), rabbit GPRIN3 (69% identical), guinea pig GPRIN3 (67% identical), dog GPRIN3 (66% identical), rat Gprin3 (60% identical), mouse Gprin3 (58% identical), tropical clawed frog gprin3 (28% identical), zebrafish gprin3b (17% identical). Paralogues in human: GPRIN2 (11% identical).
Diseases named in the same sentence as GPRIN3 in open-access papers:
GPRIN3 is named in the same sentence as 15 diseases in open-access papers, as found by Europe PMC text mining. Sharing a sentence is not in itself a finding about the gene and the disease. The quoted sentences say what the papers report.
Parkinson disease (2 papers, 2015 to 2023). A progressive degenerative disorder of the central nervous system characterized by loss of dopamine producing neurons in the substantia nigra and the presence of Lewy bodies in the substantia nigra and locus coeruleus. "The outcome of the study indicates a prevalent role of GPRIN3 in dopamine signaling in the striatum which can be linked with striatal dysfunction associated with the dopamine receptor, such as Parkinson's disease and psychiatric disorders." (PMID 37654790, 2023).
Anxiety (1 paper, 2025). Intense feelings of nervousness, tension, or panic often arise in response to interpersonal stresses. "GPRIN3-knockout mice have reduced locomotor activity, increased anxiety-like behavior in the elevated maze test, and reduced locomotor response to dopamine stimulation." (PMID 40045203, 2025).
breast carcinoma (1 paper, 2023). "Such as CMSS1 and ZHX2 in uterine cancer, OSBPL8, FAM214A in breast cancer, TPT1, GPRIN3, and VAV3 in pancreatic cancer." (PMID 37024957, 2023).
chronic obstructive pulmonary disease (1 paper, 2023). A chronic and progressive lung disorder characterized by the loss of elasticity of the bronchial tree and the air sacs, destruction of the air sacs wall, thickening of the bronchial wall, and mucous accumulation in the bronchial tree. "It has also been suggested that GPRIN3 is associated with COPD (severe chronic obstructive pulmonary disease) and emphysema, and cocaine addiction." (PMID 37686494, 2023).
kidney stone (1 paper, 2023). "Nevertheless, the biological roles of GPRIN3 in kidney stone formation is still unknown." (PMID 36932340, 2023).
tumor (3 papers, 2023 to 2024). "High expression of FOSB+, NEAT1+, or XIST+ tumor cell-associated genes such as FSTL3, VTN, PAPPA, CCN1, RRAD, and GPRIN3 may predict poor survival in patients with LUSC, suggesting that these genes act as prognosis biomarkers." (PMID 37430270, 2023). "Among these genes, six genes are potential regulator of tumor metastasis, including CEMIP, FBN2, TIAM1, ITGA2, ARHGAP42, and GPRIN3." (PMID 38971758, 2024). "In a mechanistic view, miR-6838-5p, as a tumor suppressor, prevented GC cell malignant behaviors by regulating GPRIN3 (GPRIN Family Member 3) expression and blocking Wnt/β-catenin pathway." (PMID 37386429, 2023).
GPRIN3 also shares sentences with these, for which no sentence is quoted: atherosclerosis (1 paper); cocaine addiction (1); developmental delay (1); emphysema (1); pancreatic cancer (1); Parkinsonism (1); pneumonia (1); psychiatric disorder (1); uterine cancer (1).